RBM33 (RNA binding motif protein 33)
Description:
RNA reader protein, which recognizes and binds specific RNAs, thereby regulating RNA metabolic processes, such as mRNA export, mRNA stability and/or translation. Binds a subset of intronless RNAs containing GC-rich elements, such as NORAD, and promotes their nuclear export by recruiting target RNAs to components of the NXF1-NXT1 RNA export machinery. Specifically recognizes and binds N6-methyladenosine (m6A)-containing mRNAs, promoting their demethylation by ALKBH5. Acts as an molecular adapter, which (1) promotes ALKBH5 recruitment to m6A-containing transcripts and (2) activates ALKBH5 demethylase activity by recruiting SENP1, leading to ALKBH5 deSUMOylation and subsequent activation.
Synonyms: PRR8; DKFZp686F102; MGC20460; DKFZp434D1319
Tractability: PROTAC: UniProt records ubiquitination sites on it; ubiquitination databases record sites on it; its protein half-life has been measured.
Gene: Protein-coding gene on chromosome 7 (155,644,451 to 155,781,485, forward strand). Ensembl gene ENSG00000184863.
Subcellular location: Nucleus; Cytoplasm
Subcellular location (Human Protein Atlas): Nucleoplasm
Gene Ontology:
Molecular function: lncRNA binding; N6-methyladenosine-containing RNA reader activity; protein-macromolecule adaptor activity; RNA binding; nucleic acid binding
Biological process: regulation of mRNA stability; RNA export from nucleus
Cellular component: cytoplasm; nucleus
Genetic constraint (gnomAD): Loss-of-function variants: 26 observed, 110.9 expected, observed/expected ratio (o/e) 0.23, 90% interval 0.17 to 0.32. The upper end of that interval is the gene's LOEUF score, 0.32, which puts it in group 1 of 6, group 1 being the genes least tolerant of losing a copy. Missense variants: 1,224 observed, 1,411.4 expected, observed/expected ratio (o/e) 0.87, 90% interval 0.83 to 0.91. Synonymous variants: 603 observed, 556.01 expected, observed/expected ratio (o/e) 1.08, 90% interval 1.01 to 1.16.
Homologues: Orthologues: chimpanzee RBM33 (99% identical), macaque RBM33 (99% identical), rabbit RBM33 (90% identical), dog RBM33 (89% identical), guinea pig RBM33 (88% identical), rat Rbm33 (88% identical), mouse Rbm33 (87% identical), tropical clawed frog rbm33 (52% identical), zebrafish rbm33a (38% identical), zebrafish rbm33b (16% identical).
Diseases named in the same sentence as RBM33 in open-access papers:
RBM33 is named in the same sentence as 12 diseases in open-access papers, as found by Europe PMC text mining. Sharing a sentence is not in itself a finding about the gene and the disease. The quoted sentences say what the papers report.
head and neck squamous cell carcinoma (4 papers, 2023 to 2025). A squamous cell carcinoma that arises from any of the following anatomic sites: lip and oral cavity, nasal cavity, paranasal sinuses, pharynx, larynx, and salivary glands. "The overexpression of RBM33 in human head and neck squamous cell carcinoma (HNSCC) cells has been observed to facilitate the development of HNSCC tumors by enhancing the stability of DDIT4 in a manner that is dependent on m6A modification." (PMID 39524539, 2023). "In head and neck squamous cell carcinoma (HNSCC) cells, RNA-binding motif protein 33 (RBM33) recruits ALKBH5 to m6A-marked substrates and activates its demethylase activity by removing SUMOylation." (PMID 40186131, 2025). "Functionally, RBM33 is indispensable for the progression of head and neck squamous cell carcinoma (HNSCC): by recruiting ALKBH5 to demethylate and stabilize DDIT4 mRNA, RBM33 promotes autophagy and thereby drives tumorigenesis." (PMID 41562066, 2025).
breast carcinoma (2 papers, 2021 to 2023). "For example, RBM4 inhibits the apoptosis of breast cancer cells by upregulating the expression of IR‐B and MCL‐1S and RBM33 participates in promoting proliferation in various cancers." (PMID 37395176, 2023). "In the analysis of the correlation between overall survival and significant DEG expression (CLDN7, MLLT10, RBM33, SH3RF1, SSBP4, and UBE2Z) in breast cancer, we found a shorter survival time based on GSE5881 and GSE42568 (P< 0.05)." (PMID 34151730, 2021). "Significantly overexpressed genes (CLDN7, MLLT10, RBM33, SH3RF1, SSBP4, and UBE2Z) were correlated with shorter survival, whereas underexpressed genes (BMPER, FGF7, MSRB3, and TNRC6B) were correlated with longer survival in breast cancer." (PMID 34151730, 2021). "Interestingly, other DEGs in breast cancer identified in this study, including MLLT10, RBM33, SH3RF1, UBE2Z, and TNRC6B, have not been proven in previous studies." (PMID 34151730, 2021).
cervical cancer (2 papers, 2021 to 2022). A primary or metastatic malignant neoplasm involving the cervix. "Reports show that RBM33 promotes the progression of gastric cancer by targeting miR-149 to regulate IL-6, and that the circular RNA of RBM33 is involved in the progression of cervical cancer by regulating the miR-758-3p/PUM2 axis." (PMID 35368875, 2022).
leukemia (1 paper, 2013). A malignant (clonal) hematologic disorder, involving hematopoietic stem cells and characterized by the presence of primitive or atypical myeloid or lymphoid cells in the bone marrow and the blood. "We have previously detected RBM33 circles in human leukocyte and leukemia samples and mouse brain, suggesting the possibility of evolutionary conservation." (PMID 24039610, 2013).
vascular occlusion (1 paper, 2022). "This is the first study showing that the low expression of genes associated with epigenetic regulation, such as SOX6 and RBM33, may be related to vascular occlusion in MMD, whereas the overexpression of KCNMA1 and GALNT2 may be related to the vascular hyperplasia." (PMID 35368875, 2022).
infection (1 paper, 2022). The state of being infected such as from the introduction of a foreign agent such as serum, vaccine, antigenic substance or organism. "Infection of these cells with a genome-wide lentiviral CRISPR library followed by the identification of sgRNAs that were enriched in cells with diminished fluorescence enabled the discovery that RBM33, a poorly characterized RNA binding protein, is essential for NORAD nuclear export." (PMID 35589130, 2022).
RBM33 also shares sentences with these, for which no sentence is quoted: cancer (3 papers); gastric cancer (2); abdominal aortic aneurysm (1); Behcet’s syndrome (1); Obesity (1); tumor (1).